DRC7 (dynein regulatory complex subunit 7)
Description:
Component of the nexin-dynein regulatory complex (N-DRC) a key regulator of ciliary/flagellar motility which maintains the alignment and integrity of the distal axoneme and regulates microtubule sliding in motile axonemes (By similarity). Involved in the regulation of flagellar motility (By similarity). Essential for male fertility, sperm head morphogenesis and sperm flagellum formation (By similarity).
Synonyms: C16orf50; CCDC135; DKFZp434I099; FAP50; CFAP50
Tractability: Small molecule: a structure with a bound ligand is known.
Gene: Protein-coding gene on chromosome 16 (57,694,793 to 57,731,805, forward strand). Ensembl gene ENSG00000159625.
Subcellular location: Cell projection, cilium, flagellum; Cytoplasm, cytoskeleton, cilium axoneme; Cytoplasm, cytoskeleton, flagellum axoneme
Gene Ontology:
Molecular function: protein binding
Biological process: cilium movement; flagellated sperm motility; sperm axoneme assembly; spermatogenesis
Cellular component: cytoplasm; axonemal nexin link; axoneme; motile cilium
Genetic constraint (gnomAD): Loss-of-function variants: 75 observed, 102.88 expected, observed/expected ratio (o/e) 0.73, 90% interval 0.6 to 0.88. The upper end of that interval is the gene's LOEUF score, 0.88, which puts it in group 3 of 6, group 1 being the genes least tolerant of losing a copy. Missense variants: 1,015 observed, 1,171.6 expected, observed/expected ratio (o/e) 0.87, 90% interval 0.82 to 0.91. Synonymous variants: 395 observed, 459.47 expected, observed/expected ratio (o/e) 0.86, 90% interval 0.79 to 0.93.
Homologues: Orthologues: chimpanzee DRC7 (99% identical), macaque DRC7 (97% identical), rabbit DRC7 (86% identical), guinea pig DRC7 (86% identical), dog DRC7 (84% identical), pig DRC7 (84% identical), rat Drc7 (84% identical), mouse Drc7 (83% identical), tropical clawed frog drc7 (54% identical), zebrafish ccdc135 (44% identical).
Diseases named in the same sentence as DRC7 in open-access papers:
DRC7 is named in the same sentence as 4 diseases in open-access papers, as found by Europe PMC text mining. Sharing a sentence is not in itself a finding about the gene and the disease. The quoted sentences say what the papers report.
Infertility (3 papers, 2020 to 2025). "To investigate the causes of infertility in Drc7-/- male mice, we observed testis morphology and found that Drc7-/- testes were slightly smaller than those of Drc7+/-." (PMID 31961863, 2020). "Similarly, Drc7/Ccdc135 knockout mice display truncated sperm tails and infertility, and mutations in DRC4/GAS8 have been implicated in PCD in humans." (PMID 41460250, 2025).
male infertility (2 papers, 2023 to 2024). The inability of the male to effect fertilization of an ovum after a specified period of unprotected intercourse. "The SPATA16, CFTR, KIF6, STPG2, and DRC7 mutations are associated with male infertility, specifically azoospermia, and a further examination of this genetic function is required." (PMID 37895049, 2023). "In this study, an Ampiseq targeted NGS panel and Illumina TruSeq WES were both used to pinpoint six specific genes (KIF6, DRC7, STPG2, SPATA16, CFTR, CMTM2) that play a role in MT association and spermiogenesis, which are crucial factors in understanding the causes of male infertility." (PMID 37895049, 2023). "Our experimental results have pinpointed evidence for a potential link between genetic variations in the KIF6, DRC7, and STPG2 genes with male infertility." (PMID 37895049, 2023). "Both DRC7 and KIF6 stand out as promising candidates for meaningful genetic testing in the context of male infertility." (PMID 37895049, 2023). "In terms of male infertility, the best studied gene among the N-DRC is DRC7 (MIM: 618769), which is amenable for proper assembly of the N-DRC structure (in Drc7−/− male mice, the length of the sperm tail was reduced, followed by abnormalities of sperm head morphology)." (PMID 38650655, 2024).
Meckel syndrome (1 paper, 2023). "Closely related to CEP76 and DRC7 are two inactive proteins C2D2A and C2D2B, the former being a part of the tectonic-like complex and is associated with Meckel syndrome." (PMID 37164157, 2023).
DRC7 also shares sentences with these, for which no sentence is quoted: Azoospermia (1 paper).